CXCL5 (C-X-C motif chemokine ligand 5)
Diseases named in the same sentence as CXCL5 in open-access papers (continued):
Sharing a sentence is not in itself a finding about the gene and the disease.
cancer (continued). "The effect of CXCL5 may depend on the source since it can be secreted by both cancer cells or cells in the TME such as macrophages and dendritic cells." (PMID 40589738, 2025). "CXCL5 was as the major chemokine highly upregulated in the cancer-activated CAF." (PMID 41392310, 2025). "In addition, CXCL5 plays a vital role in the creation of pre-metastatic environments and is increased in metastatic lung tissue, directing the movement of cancer cells through the CXCL5/CXCR2 pathway." (PMID 39670859, 2025). "Concentrations of biomarkers that were significantly decreased (p < 0.05) in the cohort of cancer patients included albumin, Hb, and lymphocyte count, while white blood cell counts (WBCs), neutrophil counts, and concentrations of CXCL5 and H3Cit were comparable between patients and controls." (PMID 38744744, 2024). "The studies on the effects of IL-34 and CCL25 on the TME may provide a better understanding of the clinical significance of CXCL5 in cancer immunotherapy." (PMID 39235457, 2024). "The association between CXCL5 and cancer immunotherapy is currently under investigation and has not been established." (PMID 39235457, 2024). "Research that documents raised CXCL5 levels may be questionable due to inconsistencies in its measurement, challenging the reliability of CXCL5 as a prognostic marker for cancer." (PMID 37906352, 2023). "Moreover, CAF-derived CXCL5 promotes programmed cell death-ligand-1 expression in cancer cells by activating the PI3K/Akt pathway, creating an immunosuppressive microenvironment." (PMID 37746966, 2023). "A recently discovered positive feedback loop suggests that TAN upregulates miR-301b-3p expression in cancer cells, sustains hyperactivity in NFkB signaling, and leads to increased levels of C-X-C motif chemokine 5 (CXCL5) secretion, and in turn recruit more TAN." (PMID 37035187, 2023). "CXCL5 and H3Cit as valuable biomarkers in cancer cachexia remains to be defined." (PMID 37906352, 2023). "The 4T1/GFP spheroids (S) secreted CCL5 (53 pg/mL) and CXCL5 (290 pg/mL), which are associated with a negative cancer prognosis." (PMID 37445941, 2023). "Finally, although we demonstrated that Cxcl5 is a major downstream effector of stromal Foxf2 in the RM-1 model, we cannot exclude potential roles of other cytokines in human cancers." (PMID 36369237, 2022). "CAFs are positively related to PD-L1 expression in CRC tissues, and by secreting CXCL5, CAFs could promote the expression of PD-L1 in cancer cells." (PMID 36389763, 2022). "CXCL5/ENA-78, commonly known as a strong neutrophil chemoattractant and a powerful mediator of inflammation, was shown to contribute to the promotion of cancer cell migration and invasion, associated with the activation of the EMT process by the ERK/GSK-3β/Snail pathway." (PMID 35406619, 2022). "Thus, the aim of the present study was to examine the expression of CXCL5 in PC and to evaluate the usefulness of serum CXCL5 levels as a potential cancer biomarker for PC." (PMID 33458757, 2021). "Another study revealed that early-life exposure to microbiota can induce microbial enduring and host changes that lead to colitis-associated cancer susceptibility, during which enhanced expression of CXCL1, CXCL2, and CXCL5 attracts G-MDSC to generate an immunosuppressive environment." (PMID 34689842, 2021). "CXCL5 was thought to play roles in cell proliferation, migration, and invasion of cancer." (PMID 34194499, 2021). "Cancer cell DDR1-induced CXCL5 mediates NET formation and NET-induced cancer cell invasion." (PMID 34237033, 2021). "Our initial analysis identified CXCL5 as a cancer-related gene highly expressed in PC." (PMID 33458757, 2021). "There are many reports on the mechanism of CXCL5 promoting cancer progression." (PMID 33869023, 2021). "In addition, ROC analysis showed that CXCL5 had a sensitivity of 68.4% and a specificity of 90.3% to discriminate cancer recurrence (cutoff value: 442.75 pg/ml; AUC, 0.832)." (PMID 33458757, 2021).
cancer (continued). "Considering the high behavioral similarity between trophoblast cells and cancer cells, we hypothesized that CXCL5 may influence trophoblast invasion, and its expression levels in villous tissue may be correlated with RSA." (PMID 34603292, 2021). "In line with previous reports, this could be the response of the cancer and its microenvironment to an immune attack, suggesting that CXCL5 is a potential Achilles’ heel." (PMID 34206815, 2021). "In addition, CXCL5 induced these neutrophils to form NETs that aided cancer cell invasion and metastasis." (PMID 35127700, 2021). "CXCL5 plays an important role in the development and progression of many cancers." (PMID 32632106, 2020). "Importantly, CD68 macrophages expressing CXCL5 were found within the cancers and with significantly higher numbers in the stroma around the nests of cancer cells." (PMID 33149188, 2020). "Recent evidence has shown that CXCL5 could promote carcinogenesis and cancer progression in a variety of cancer types." (PMID 32201508, 2020). "Many studies have shown that CXCL5 promotes cancer progression." (PMID 33061849, 2020). "Given the critical roles of CCL2 and CXCL5 in recruiting TAMs to neoplastic tissue, thereby contributing to cancer metastasis 30, 31, we investigated whether S100A14 plays a key role in orchestrating the recruitment of macrophages through CCL2 and CXCL5." (PMID 32483412, 2020). "We further evaluated the prognostic value of CXCL5 in certain types of cancer." (PMID 29743818, 2018). "Accumulating evidence suggests that CXCL5 may participate in cancer-related inflammation, which is involved in many aspects of malignancy in cancer biology." (PMID 29743818, 2018). "Recent studies have revealed that CXCL5 could serve as a potential prognostic biomarker for patients with cancer." (PMID 29743818, 2018). "Furthermore, using Cox multivariate analysis in eight studies including ten cohorts, we found that elevated CXCL5 expression levels was an independent prognostic factor for OS in cancer patients (HR 1.65, 95% CI 1.24–2.20, p = 0.001)." (PMID 29743818, 2018). "Recent studies have demonstrated that CXCL5 could serve as a potential prognostic biomarker for cancer patients." (PMID 29743818, 2018). "Therefore, we performed the current quantitative meta-analysis to elucidate the prognostic significance of CXCL5 expression in cancer patients." (PMID 29743818, 2018). "Considering the important functions of CXCL5 in cancer, studies have demonstrated that CXCL5 could serve as a potential prognostic biomarker for cancer patients." (PMID 29743818, 2018). "In conclusion, our meta-analysis suggested that elevated CXCL5 expression might be an adverse prognostic marker for cancer patients, which could help the clinical decision making process." (PMID 29743818, 2018). "In addition, by combining HRs from Cox multivariate analysis, we found that CXCL5 was an independent prognostic factor of OS in cancer patients." (PMID 29743818, 2018). "Cancer cells are then attracted to the metastatic site via the CXCL5/CXCR2 axis." (PMID 28186102, 2017). "The pro-angiogenic cytokine CXCL5 can also enhance the growth and invasion of cancer cells." (PMID 28399860, 2017). "CXCL5, which has been reported to function for various cancer development, has been confirmed to be a direct target of miR-4284, suggesting that CXCL5 might be also involved in BBMD3′s effect." (PMID 28052018, 2017). "Notably, several of the cytokines whose expression was upregulated in parenchymal cancer cells (e.g. CCL2, CCL7, CXCL1, CXCL2, CXCL5, CCL20) have been implicated in the attraction of immune cells." (PMID 27203741, 2016). "Moreover, enhanced production of CXCL5 by cancer cells gives rise to the systemic secretion of granulocyte/monocyte colony stimulating factor (GM-CSF), a cytokine that contributes to the maintenance of the MDSC pool in the bone marrow." (PMID 24429391, 2014).
cancer (continued). "Moreover, cancer cells with disabled TGFß machinery produce high levels of CXCL5 when confronted with persistent TGFß ligand, both in an autocrine and a paracrine fashion." (PMID 24429391, 2014). "More recently, CXCL5 contribution to cancer growth and metastasis has been demonstrated." (PMID 24500664, 2014). "In addition, the same group recently revealed a correlation between KLF4 expression and production of the C-X-C motif chemokine CXCL5 (CXCL5) by primary cancer cells." (PMID 24429391, 2014). "The CXCL5 expression has been shown to be elevated at both mRNA and protein levels and affect patients’ survival in a number of human tumors, including in pancreatic, colorectal, breast, ovarian, or prostate carcinomas." (PMID 24500664, 2014). "Moreover, drug development strategies targeting CXCL5 in cancer, such as small-interfering RNAs, small molecules, or antibodies, may focus on cachexia prevention as a therapeutic readout in future clinical trials." (PMID 41392310, 2025). "Many studies have demonstrated that CXCL5 could promote cancer progression via the receptor CXCR2." (PMID 36151545, 2022). "In addition, CXCL5 was shown to have potent effects on neutrophil recruitment in cancer." (PMID 29743818, 2018). "CXCL5 could activate multiple signaling pathways to promote the progression of cancer." (PMID 29743818, 2018). "Furthermore, we evaluated the prognostic value of CXCL5 in certain types of cancer." (PMID 29743818, 2018). "Meanwhile, neutrophils could potentiate cancer cell migration, invasion and dissemination by secreting immunoreactive molecules such as hepatocyte growth factor, oncostatin M, b2-integrins or neutrophil elastase, which might be another mechanism for CXCL5 promoting cancer progression." (PMID 29743818, 2018). "However, we found that CXCL5 was primarily secreted by cancer cells in CRC." (PMID 28356111, 2017). "Thus LCCs might act as the producer and receptor of CXCL5 in the development and metastasis of the cancer and may themselves play a critical role in the initiation and formation of inflammatory microenvironment like other cancer cells." (PMID 25011526, 2014). "In complete responders, skin lesion RNA sequencing after treatment, compared with baseline, identified increased inflammation (CXCL5, CXCL8, IL1A, COL1A1) and downregulated cancer markers (PRAME, S100B, MLANA, STK32A)." (PMID 42316430, 2026). "CXCR2, a receptor for chemokines like CXCL5 (ENA-78) and CXCL8 (IL-8), is involved in various aspects of cancer biology." (PMID 41149503, 2025). "Heatmap analyses revealed that GPATCH3 expression was broadly negatively correlated with chemokines such as CXCL5 and CXCL8, as well as immunostimulatory molecules including CD40LG and TNFSF15, in a pan-cancer context." (PMID 40861452, 2025). "CAFs in turn, secrete C-X-C motif chemokine 5 (CXCL5), which binds to c-x-c motif chemokine receptor 2 (CXCR2) on cancer cells, resulting in PI3K pathway activation and downregulation of PD-L1." (PMID 40362630, 2025). "CXCL5 treatment alone induced myotube atrophy and inhibited myogenic ERK1/2 signaling, similar to cancer-activated CAF treatment." (PMID 41392310, 2025). "Our results show that CXCL5 treatment can induce myotube atrophy and CXCR2 expression is upregulated in the skeletal muscle of mice transplanted with cancer cells plus CAF." (PMID 41392310, 2025). "Similar to the mouse cell lines, PLX51107 treatment of human cancer cell lines resulted in reduced protein levels of CCL2 and CXCL5 (P < 0.01)." (PMID 40762981, 2025). "The effectors of migration and apoptosis in other cancers and developing tissues were differentially expressed: LCP1 and CXCL5 were upregulated, while PROSER2 and PCDHA6 were downregulated." (PMID 40323130, 2025). "Candidate biomarkers such as IL-7, TWEAK, 4E-BP, CXCL5, and CD5 are all actively involved in cancer initiation and progression in previous reports, and the KEGG analysis also indicated cancer pathway enrichment." (PMID 38455059, 2024).
cancer (continued). "CXCL5 recruits TAM into the TME and promotes TAM polarization and abundance, leading to active glycolysis in cancer cells and thereby promoting cancer cell proliferation and survival." (PMID 38434684, 2024). "TCGA database indicated that among several ligands, CXCL1, CXCL3, CXCL5, CXCL7 and CXCL8 (ligands for CXCR2) and CCL15 (ligand for CCR1) were particularly upregulated in CRC tissues compared with other cancers." (PMID 38750114, 2024). "These include broad decreases in cytokine release, increased cancer-promoting chemokines (CXCL1 and CXCL5) and increased immunosuppressive surface proteins that likely facilitate T-cell suppression." (PMID 38542481, 2024). "Gem treatment increased cancer cell nuclear Yap1, CXCL5, and fibroblast Cox2 in KPC tumors, while 14-3-3ζ knockout diminished Gem-induced nuclear Yap1, CXCL5, and Cox2 expression." (PMID 39468013, 2024). "We selected eight candidates (CST4, CCL20, CX3CL1, CXCL5, CXCL8, GDF15, CCL5 and MMP3) that play an important role in cancer pathogenesis for further study." (PMID 38385965, 2024). "Protein expression of CXCL5/CXCR2 and CXCL12/CXCR4 were decreased with KT treatment, resulting in KT inhibiting cancer cells’ secondary growth within the bone." (PMID 36674719, 2023). "The CXCL5/CXCR2 axis stimulates bone colonization, which is also a step for cancer cell stability in bone." (PMID 36674719, 2023). "Transcriptome analysis revealed that CHRM3 knockdown significantly reduced an array of classic factors in cancer invasive growth including MMP1/MMP3/MMP10/MMP12 and CXCL1/CXCL5/CXCL8." (PMID 37744266, 2023). "According to reports, celecoxib inhibits NF-kB by boosting the IkB inhibitor protein, lowering blood levels of CXCL5, and blocking the AKT/NF-kB pathway that is involved in cancer and angiogenesis." (PMID 37580670, 2023). "Meanwhile, the interleukin 6 (IL6), CXC chemokine Ligand-5 (CXCL5), and CXC chemokine Ligand-10 (CXCL10) expressions were inhibited, and the cancer-promoting effect was reversed by COL12A1 knockdown." (PMID 36900272, 2023). "Transcriptome analysis revealed that CHRM3 knockdown significantly reduced an array of classic factors involved in cancer invasive growth, including MMP1/MMP3/MMP10/MMP12 and CXCL1/CXCL5/CXCL8." (PMID 37744266, 2023). "The relative levels of CXC chemokines (A), CXCL5 (B) and CXCL16 (D) in multiple cancer types and the relative levels of CXC chemokines in PDAC (C)." (PMID 35468838, 2022). "It was observed that CXCL5 mediates inflammation by activating the PI3K/AKT and the MAPK/ERK1/2 signaling pathways to promote cancer progression." (PMID 36612163, 2022). "Measurements of serum expression levels in cancer patients undergoing cisplatin treatment have earlier been explored for four of these inflammatory proteins, namely, FASLG, CXCL5, CD5, and IL-12." (PMID 35682983, 2022). "The CXCL5-neutralizing antibody significantly reduced MDA-PATC 148 and BxPC-3 cell–induced histone H3 citrullination, NET formation, and cancer cell invasion." (PMID 34237033, 2021). "Together, these results provide evidence that DDR1 stimulates CXCL5 production through a PKCθ/SYK/NF-κB signaling cascade and that CXCL5 from cancer cells induces neutrophils to form NETs and thereby enhances metastasis." (PMID 34237033, 2021). "CTX also inhibits chemokines that bind to CXCR1 and CXCR2 receptors such as CXCL5, CXCL1/2/3, CXCL1a, CXCL6, and CXCL8 (IL-8) that are involved in cancer angiogenesis and metastasis." (PMID 34822613, 2021). "Among them, a gradual increase from early-stage cancer to more advanced stages were strongest for APOC2 and IL8 genes followed by for SAA4 and OSM genes, whereas HIST1H1E, PF4V1, CXCL5, and IL2RA expression showed limited stage-wise upregulation." (PMID 33828156, 2021). "IL-17 is proclaimed to increase CXCL5 expression of cancer cell, and subsequently enhancing the infiltration of MDSC into the cancer cell cluster in a CXCL5/CXCR2-dependent manner." (PMID 34689842, 2021).
cancer (continued). "Numerous studies have confirmed that CXCL5 can induce the epithelial-to-mesenchymal transition (EMT) process in cancer cells and thus promotes cancer cells invasion and metastasis." (PMID 34603292, 2021). "During cancer progression, cancer cell-derived CCL2, CCL5, CXCL8, and CXCL5 are released and recruit immunosuppressive-myeloid cells into the TME, including MDSCs, TAMs, and TANs through CXCR2 activation." (PMID 35127700, 2021). "Conversely, recombinant human CXCL5 induced histone H3 citrullination, NET formation, and cancer cell invasion in MDA-PATC 148KD#32 cells." (PMID 34237033, 2021). "The combination of CXCL5 and CXCR2 exerts a strong granulocyte chemotaxis and angiogenesis effect, and CXCL5/CXCR2 axis plays an important role in mediating the infiltration and metastasis of malignant tumors." (PMID 33869023, 2021). "We then checked the expression of pERK in CXCL5 treated CCA cells, since ERK has been shown to activate downstream EMT and MMP gene expression thus increasing cancer cell migration in different cancer types." (PMID 34831316, 2021). "Recently, studies on CXCL1, CXCL5, and CXCL7 mainly focus on the biomarker and pathogenesis of various malignant tumors, but a few about CNS IIDDs existed." (PMID 32515897, 2020). "A recent study showed that overexpression of CXCL5, CXCL9, and CXCL10 improved the immune function of cancer patients." (PMID 33323542, 2020). "The CXCL5 is a member of the CXC chemokines subfamily, which promotes angiogenesis and remodelling of connective tissues and hence plays important role in cancer cell proliferation, migration and invasion." (PMID 32545325, 2020). "Cancer cells secrete chemokine (C-C motif) ligand 5 (CCL5) to attract immunosuppressive Tregs, C-X-C motif chemokine 5 (CXCL5) to recruit neutrophils and colony-stimulating factor-1 (CSF-1) to attract macrophages." (PMID 32397303, 2020). "Bioinformatic analyses, performed to assess the role of 41 cytokines after RT exposure and their network interactions, suggested TGF-β, MIF, CCL2, CXCL5, CXCL8 and CXCL12 as master regulators of cancer immune escape in RMS tumors." (PMID 32854690, 2020). "YAP activity in cancer cells induces the expression of cytokines such as IL-6 (interleukin 6), CXCL5 (C-X-C motif chemokine 5), and granulocyte-macrophage colony stimulating factors that stimulate the recruitment of myeloid-derived suppressor cells (MDSCs)." (PMID 31817001, 2019). "CXCL5 is a member of the CXC-type chemokine family, which has been found to play important roles in tumorigenesis and cancer progression." (PMID 29743818, 2018). "This enabled us to examine genes on an individual basis, and many genes important in the development of CRC, and cancer in general, were upregulated in the CAP tissues relative to the CFPs, including CXCL5, GREM1, IGF2, CTGF and PLAU." (PMID 29453410, 2018). "Hyperactivated Hippo-YAP signaling in driving upregulation of CXCL5 via the YAP–TEAD complex and stimulating MDSC recruitment have been identified in cancer cells." (PMID 30072984, 2018). "In line with their high potential for functional impact, CXCL1, CXCL5, CCL2, and IL-8 were also significantly induced by TRAIL in different cancer cell lines, as determined by ELISA, antibody-based cytokine array, and qPCR." (PMID 28212753, 2017). "Together, our results indicate that 3D condition, but not 2D condition, elicits the cancer-intrinsic role of Cxcl5 for the growth of a variety of mouse and human cancers." (PMID 40050422, 2025). "Nevertheless, the differential expression of EGFR and VEGFc, in addition to MMP9 and CXCL5, differentially packaging into IRF5-low versus IRF5-high EVs across two cancer types provide insight into the mechanisms by which IRF5 contributes to protection from PMN formation." (PMID 38969706, 2024).